CKS2 (CDC28 protein kinase regulatory subunit 2)
Diseases named in the same sentence as CKS2 in open-access papers (continued):
Sharing a sentence is not in itself a finding about the gene and the disease.
tumor (55 papers, 2006 to 2026). "CKS2 is an oncogene that is aberrantly expressed in various malignant tumor tissues, including BC, and is closely associated with various biological processes such as tumor development, progression, and metastasis." (PMID 41010991, 2025). "As a cell cycle-associated protein, CKS2 plays an important role in tumor progression and prognosis." (PMID 39188686, 2024). "The results indicated a significant association between CKS2 overexpression in tumor tissues and poor overall survival (OS) in patients with BL and DLBCL (log‐rank p = 4.8e‐12; log‐rank p = 8.7e‐6)." (PMID 39560180, 2024). "The CKS2 immunohistochemical score was mainly linked with lymph node metastasis, pathological tumor stage, spread through air spaces (STAS), histological subtypes, and pathological differentiation." (PMID 36010686, 2022). "The association between CKS2 expression level and tumor immune infiltration was explored using the single-sample Gene Set Enrichment Analysis (ssGSEA) and TIMER database." (PMID 34729099, 2021). "Indeed, numerous studies have reported abnormal overexpression of CKS2 in various malignant tumors, where it has been implicated in promoting tumor progression and drug resistance." (PMID 39560180, 2024). "Studies have linked increased CKS2 levels in malignant lymphocytes to tumor proliferation." (PMID 39560180, 2024). "CKS2 plays a significant role in cell cycle regulation and is implicated in tumor progression." (PMID 39560180, 2024). "Furthermore, CKS2 was associated with increased tumor size and poor overall prognosis in patients with uLMS." (PMID 37373974, 2023). "Moreover, the cyclin kinase subunit CKS2 was upregulated; CKS2 expression was increased in several types of cancer and associated with tumor progression." (PMID 26894977, 2016). "Finally, we reported inhibition of TGFβ/SMAD pathway (by TGFβ inhibitor LY2157299 or SMAD4 siRNA) could reverse the tumor‐promoting effects caused by CKS2." (PMID 36284444, 2023). "Besides, we selected 5 key genes (SRSF2, HELLS, PNN, TK1, and CKS2) in hallmark_E2F_targets in Pathcards database and validated that they are associated with overall survival, metastasis, and tumor stage of patients with PCa through multiple online database validation." (PMID 35392496, 2022). "The expression of both hsa_circ_0001946 and CKS2 was significantly upregulated in tumor tissues compared to that of matched adjacent normal tissues, whereas that of miR-7-5p was markedly downregulated." (PMID 41010991, 2025). "To further verify the effect of CKS2 expression on the proliferation of MM cells in vivo, we constructed an RPMI-8226 cell line with stable knockdown of CKS2 and constructed an MM xenograft tumor nude mouse model by subcutaneous tumor formation." (PMID 40092696, 2025). "Emerging evidence positions CKS2 as a critical oncoprotein, with its overexpression strongly correlated with tumor progression and adverse clinical outcomes across various malignancies." (PMID 40092696, 2025). "CKS2 overexpression correlates with aggressive tumor phenotypes in CRC, suggesting its role in driving malignancy." (PMID 41614789, 2025). "Despite previous findings suggesting the CKS2 gene's role in promoting tumor cell proliferation in malignant lymphocytes, the precise underlying mechanism remains incompletely understood." (PMID 39560180, 2024). "Abnormal expression of CKS2 mediates cell cycle regulation, tumor invasion, metastasis and apoptosis during the development of malignant tumors." (PMID 39188686, 2024). "In summary, abnormal expression of CKS2 in a variety of human malignant tumors can lead to the occurrence and development of cancer, and plays a role in almost all biological aspects of tumor (proliferation, migration, invasion, and drug resistance)." (PMID 39188686, 2024). "Inhibition of CKS2 can inhibit cell proliferation and invasion in vitro and reduce tumor growth in vivo." (PMID 39188686, 2024).
tumor (continued). "We conducted immunohistochemical (IHC) analysis to assess CKS2 protein level in samples from non‐tumor lymph nodes, BL, and DLBCL." (PMID 39560180, 2024). "Studies have confirmed that the overexpression of CKS2 is closely related to the tumor aggressiveness and prognosis of various malignant tumors." (PMID 39188686, 2024). "Knockdown of CKS2 can inhibit cell proliferation, induce cell cycle S phase, G2/M phase arrest and apoptosis in vitro, and reduce tumor growth in vivo." (PMID 39188686, 2024). "This suggests that CKS2 can be used not only as a means of clinical diagnosis and prognosis of tumor patients, but also as a potential therapeutic target." (PMID 39188686, 2024). "Overexpressed CKS2 contributes to the development and progression of CRC and is also significantly associated with tumor differentiation and lymph node metastasis." (PMID 39188686, 2024). "Our results further showed that downregulation of DLX4 suppressed YB-1 expression, which further suppressed CKS2 expression, thereby suppressing tumor growth of NSCLC." (PMID 37744456, 2023). "Recently, CKS2 is widely accepted as a key tumor regulator, increasing number of researches have found that CKS2 gene copy number are increased in the various tumorigenesis and are correlated to the poor prognosis." (PMID 36284444, 2023). "We found that downregulation of DLX4 inhibited YB-1 expression, which in turn suppressed CKS2 expression, thus inhibiting tumor growth." (PMID 37744456, 2023). "Downregulation of DLX4 inhibited YB-1 expression, and suppressed CKS2 expression, thereby inhibiting tumor growth of NSCLC." (PMID 37744456, 2023). "As a cell cycle-related protein, CKS2 has an essential role to play in tumor progression and prognosis." (PMID 36010686, 2022). "Among 80 specimens of OS, 93.75% showed moderately or strongly positive immunostaining of CKS2, while in non-tumor samples, 80.49% were stained negatively or weakly positive, and no strongly positive tissues were observed." (PMID 35410253, 2022). "In this study, CKS2 was closely correlated with TMB and MSI, which also explained the vital role CKS2 plays in tumor immunity." (PMID 35663965, 2022). "We constructed a nomogram that combined CKS2 expression data with clinical prognostic characteristics, including age, tumor grade, and IDH status." (PMID 35663965, 2022). "Moreover, recovery of CKS2 by lentivirus-mediated overexpression of CKS2 in CKS2-KD cells (CKS2_Rescue) restored expression of CKS2 in both RNA and protein levels and rescued cancer-associated phenotypes including cell proliferation, colony formation, EdU staining and tumor xenograft growth." (PMID 36096885, 2022). "In the public database, a total of 9 mRNA microarrays, including 134 OS samples and 39 non-cancer samples were used to obtain expression trend of CKS2 between tumor and non-tumor samples." (PMID 35410253, 2022). "The expression level of CKS2 is closely related to tumor immunity, including the correlation of tumor immune cell infiltration, immune score, and co-expression of multiple immune-related genes." (PMID 35663965, 2022). "That is, these proteins, together with CKS2, promote tumor growth by regulating the cell cycle of tumor cells." (PMID 36010686, 2022). "The role of CKS2 in tumor immunity has been evaluated in many aspects, including cellular immune infiltration, co-expression of immune-related genes, immune score, immune checkpoint, and sensitivity to chemotherapy." (PMID 35663965, 2022). "We verified 8 key genes by putting them on the UALCAN website and found that the expression level of CKS2 in tumor tissues was higher than that in normal tissues (P = 1.62E-12)." (PMID 35984176, 2022).
tumor (continued). "A growing body of evidence has indicated that CKS2 exhibited upregulation in a variety of human cancers and contributed to tumor progression." (PMID 35693634, 2022). "Upregulation of CKS2 promoted cell proliferation and tumor formation while depletion of CKS2 led to reduced cell proliferation, delayed DNA replication and decreased clonogenic growth." (PMID 36096885, 2022). "P1 was enriched for cell cycle genes (e.g., TOP2A, UBE2C, CKS2), thus defined as cycling tumor cells." (PMID 35860547, 2022). "Particularly, the impact of CKS2 expression on biological processes such as cell cycle regulation and migration of tumor cells has been verified in other human cancers." (PMID 35693634, 2022). "While bioinformatic analyses revealed that CKS2 expression is negatively correlated with immune cell infiltration, further studies are needed to investigate the specific role of CKS2 in the tumor microenvironment." (PMID 34729099, 2021). "Overall, our study explored the potential role of CKS2 in tumor pathogenesis and demonstrated its value as a potential LUAD biomarker." (PMID 34729099, 2021). "Our results revealed that the expression of CKS2 was elevated in MPM tumor tissues compared to normal tissues and it was harmful for the prognosis of MPM patients, which is in line with these previous findings of other types of tumor." (PMID 32849853, 2020). "We also evaluated 72 pairs resected samples, results revealed that upregulation of CKS2 and RMI2 in lung ACA were associated with larger tumor size." (PMID 33083148, 2020). "Further multivariate analyses demonstrated that CKS2 expression (P = 0.014), tumor size (P = 0.021), portal vein invasion (P = 0.007), and TNM stage (P = 0.01) were independent prognostic factors for overall survival of HCC patients." (PMID 31781310, 2019). "Univariate analysis indicated that tumor size, differentiation, HBV infection, AFP, portal vein invasion, TNM stage, metastasis, and CKS2 expression were associated with OS of HCC patients." (PMID 31781310, 2019). "The genes, ZWINT, E2F1, HMGB2, KPNA2, and CKS2, were expressed at low or moderate levels in non-tumor tissues." (PMID 31695969, 2019). "The fact that both CKS1 and CKS2 are often overexpressed in primary cancers and tumour-derived cell lines suggests that neoplastic cell proliferation depends on a carefully balanced signalling network in which both proteins partake." (PMID 28939057, 2018). "qPCR analyses revealed that the mRNA levels of CKS2 were significantly increased in the CRC tissue compared with the adjacent non-tumor and normal colorectal tissues." (PMID 24137409, 2013). "The results revealed that the overexpression of CKS2 at the protein level was significantly correlated with tumor size, differentiation and pathological tumor node metastasis (pTNM) stage." (PMID 24137409, 2013). "Regarding CKS2, the only report on this subject correlated CKS2 expression at tissue level, with tumor stage." (PMID 20920335, 2010). "In addition, through the xenograft tumor model, we found that knocking down CKS2 can inhibit MM cell proliferation in vivo." (PMID 40092696, 2025). "In addition, CKS2 can also promote tumor progression by inhibiting cancer cell apoptosis induced by chemotherapy drugs and reducing cell adhesion." (PMID 39188686, 2024). "Downregulating CKS2 also slowed the growth of tumor xenografts in nude mice." (PMID 38920989, 2024). "Previous studies have shown that abnormally high expression of CKS2 may act as an oncogene in the occurrence of various malignant tumors, and participate in carcinogenesis and tumor progression as well as maintenance of cancer cell phenotype." (PMID 39188686, 2024). "In addition, CKS2 can promote tumor cell proliferation and inhibit apoptosis induced by common chemotherapy drugs." (PMID 39188686, 2024). "Additionally, the potential synergistic anti‐tumor effects of CKS2 knockdown in combination with etoposide in BL and DLBCL were explored for the first time." (PMID 39560180, 2024).
tumor (continued). "Furthermore, our investigations demonstrated that combining CKS2 silencing with etoposide synergistically inhibited tumor proliferation and induced apoptosis in BL and DLBCL." (PMID 39560180, 2024). "Our findings suggest that CKS2‐shRNA may serve as a sensitizer to enhance the sensitivity of tumor cells to chemotherapy drugs, providing experimental evidence for potential clinical applications in BL and DLBCL." (PMID 39560180, 2024). "Similar to luminal cluster 2 in primary tumour, cluster 3 in lung mets, was enriched in a proliferation gene signature (Ran, Cks1b, and Cks2), whereas cluster 2 (homologous to cluster 3 in primary tumour), expressed a mesenchymal-like gene set (Col18a1, Vcam1, Col1a1, Vim, Sparc)." (PMID 38238426, 2024). "Indeed, accumulating findings showed that CKS2 expression was abnormally elevated in several tumors and acted as a tumor‐promotive biomarker." (PMID 36284444, 2023). "CKS2 is a promising biomarker contributing to CRC tumor development." (PMID 36900162, 2023). "We are the first team to compare the expression trend of CKS2 in OS and non-tumor tissues." (PMID 35410253, 2022). "In contrast, lower CKS2 expression increased the sensitivity of tumor cells to carboplatin." (PMID 36010686, 2022). "Analysis of microarray in-house showed that expression of CKS2 mRNA in OS tissues had an elevated trend, and the ROC curve (AUC = 1) indicated that it possessed a strong ability to distinguish OS from non-tumor tissues." (PMID 35410253, 2022). "CKS2 expression in the normal brain and tumor tissue was compared." (PMID 35663965, 2022). "CKS2 overexpression accelerated tumor progression and worsened the prognosis for LUAD patients." (PMID 36010686, 2022). "The evidence chain composed of our study materials includes analysis of differential expression profiling, SMD, and sROC containing IHC, microarrays, and public datasets showed that CKS2 is significantly up-regulated in OS and has a strong distinction ability between OS and non-tumor tissues." (PMID 35410253, 2022). "The mean tumor weight of the CKS2_KD group was significantly reduced." (PMID 36096885, 2022). "In addition to its regulatory role in cell cycle transformation, CKS2 also plays a role in tumor development by promoting tumor growth and occurrence, promoting proliferation under tumor stress, and inhibiting programmed cell death." (PMID 35663965, 2022). "Depletion of CKS2 delayed tumor xenograft growth of Y79 cells in nude mice." (PMID 36096885, 2022). "Downregulation of CKS2 also slowed tumor xenograft growth in nude mice." (PMID 36096885, 2022). "Finally, the correlation between CKS2 expression and the level of immune cell infiltration was analyzed using the single-sample Gene Set Enrichment Analysis (ssGSEA) and Tumor Immune Estimation Resource (TIMER) database." (PMID 34729099, 2021). "Investigators also found that CKS2 may advance tumor progression by promoting tumor cell proliferation and regulating apoptosis." (PMID 32849853, 2020). "Similarly, for DFS of HCC patients, univariate analyses revealed that CKS2 expression, tumor size, AFP, portal vein invasion, HBsAg, TNM stage, and metastasis were potential factors." (PMID 31781310, 2019). "Additionally, enrichment analysis in KEGG pathways and GO terms revealed that CKS2-correlated genes were enriched in the cell cycle and DNA replication pathways, which are known as important factors in the proliferation of tumor cells." (PMID 31781310, 2019). "CKS2 expression levels positively correlate with copy number in 15 tumor cell lines." (PMID 29764514, 2018). "Our database mining showed that many types of tumor overexpress CKS2." (PMID 29764514, 2018). "We hypothesize that while tumor cells overexpressing Cks1, Cks2, or both, can override the replication stress checkpoint, this renders them vulnerable to nucleoside analog drugs under conditions of replication stress, e.g., triggered by methotrexate." (PMID 29383129, 2017).
tumor (continued). "The replicative and DNA damage response defects observed in Cks2−/− cells may suggest a role for CKS2 as a tumor suppressor." (PMID 22898779, 2012). "Overexpression of CKS2 has been associated with oncogenic roles but this is not mutually exclusive of a potential role as a tumor suppressor." (PMID 22898779, 2012). "Conversely, hTERT and CKS2 transcript levels were significantly up regulated in superficial forms, remaining almost unchanged in the invasive ones, thus suggesting a possible involvement of both of them in the early events during tumor development." (PMID 20920335, 2010). "At present, this is the only work to describe a possible role of CKS2 in this neoplasia." (PMID 20920335, 2010). "Furthermore, inhibiting CKS2 promoted tumor ferroptosis by downregulating GPX4 expression." (PMID 39548421, 2024). "From these results, it can be inferred that CKS2 may play a role as a tumor oncogene." (PMID 39188686, 2024). "Therefore, CKS2 is considered as a tool for cancer diagnosis and prognosis and may be a promising tumor biomarker and therapeutic target." (PMID 39188686, 2024). "The high expression of CKS2 could distinguish OS from non-tumor tissues fairly (AUC = 0.953)." (PMID 35410253, 2022). "In addition, expression inhibition of TMPO, TOP2A, RFC3, GINS1, and CKS2 genes could prevent tumor growth and TRIB3 expression suppression would be a favorable target for anti−angiogenic therapy." (PMID 34249670, 2021). "Furthermore, expression inhibition of TMPO, TOP2A, RFC3, GINS1, and CKS2 genes could prevent tumor growth." (PMID 34249670, 2021). "Furthermore, these data clearly demonstrated that the overexpression of CKS2 was significantly correlated with tumor differentiation and lymph node metastasis, which may have contributed to the development of CRC." (PMID 24137409, 2013). "PLK1 and Cyclin-dependent kinases regulatory subunit 2 (CKS2) can drive mitosis and cell cycle progression in tumor cells through deubiquitination, suggesting that OTUD6A is a potential therapeutic target for cancer." (PMID 41050073, 2025). "Statistical analysis showed that the CKS2 protein level was significantly increased in BL and DLBCL tissues compared to non‐tumor lymph nodes (p < 0.0001)." (PMID 39560180, 2024). "Immunohistochemical staining confirmed increased CKS2 protein levels in BL and DLBCL tissues, predominantly localized in the nucleus, compared to non‐tumor lymph nodes." (PMID 39560180, 2024). "The analysis of integrated expression status demonstrated up-regulation of CKS2 in OS (SMD = 1.57, 95%CI [0.27–2.86]) and the significant power of CKS2 expression in distinguishing OS samples from non-tumor samples (AUC = 0.97 95%CI [0.95–0.98])." (PMID 35410253, 2022). "There are 109 co-DEGs between the GSE75037 and GSE32863 datasets, and CKS2 and RMI2 had the relative high degrees at 32 and 23, manifesting that these two genes act a pivotal part in the genesis and progression of tumor." (PMID 33083148, 2020). "We further validated CKS2 and RMI2 using clinical biopsy samples and demonstrated that higher expression of these two genes correlates with larger tumor size and poor clinical outcomes." (PMID 33083148, 2020). "However, accumulating evidence indicated that CKS2 might contribute to tumor progression." (PMID 31781310, 2019). "In particular, we identified genes with major roles in mitosis, such as CDC28 protein kinase regulatory subunit 2 (CKS2) and cyclin E2 (CCNE2), which have been reported as over-expressed in various types of tumours." (PMID 19809427, 2009). "One group was associated with rapid proliferation, oxidative phosphorylation, invasiveness, and tumor size (MRPS23, MRPL11, CKS2, LSM3, TBX3, MSN) and another with hypoxia tolerance, anaerobic metabolism, and high lactate content (PDK2, KLF3)." (PMID 17054779, 2006).